VANGL2 (VANGL planar cell polarity protein 2)
Diseases named in the same sentence as VANGL2 in open-access papers (continued):
Sharing a sentence is not in itself a finding about the gene and the disease.
deafness (1 paper, 2024). An inherited or acquired condition characterized by the complete loss of the ability to hear from one or both ears. "We therefore chose to examine impact of VANGL2 VUS in stereocilia orientation in the lateral line system in view of the family exhibiting deafness with the p.(Glu465Ala) variant (Family 15)." (PMID 37815931, 2024). "In contrast we have been referred three new families (Families 14–16) where several members carry VANGL2 missense alleles and display neurological defects, CHD, laterality disturbance or deafness." (PMID 37815931, 2024).
embryonal rhabdomyosarcoma (1 paper, 2022). A poorly circumscribed morphologic variant of rhabdomyosarcoma. "A published dataset investigating transcriptomic differences between five skeletal muscle and 101 rhabdomyosarcoma patient samples (GSE108022) found that VANGL2/RHOA, components of WNT signalling, were important in the regulation of growth and self-renewal of embryonal rhabdomyosarcoma (ERMS) cells." (PMID 35589804, 2022).
gestational diabetes mellitus (1 paper, 2023). "In the present study, we found that Vangl2 mutation caused dysbiosis that was in line with microbiota alterations associated with obesity and gestational diabetes mellitus." (PMID 38068802, 2023). "Additionally, the dysbiosis observed in Vangl2 mutants resembles the dysbiosis seen in situations of obesity and gestational diabetes mellitus, both of which are risk factors for NTDs." (PMID 38068802, 2023). "At the phylum level, Vangl2+/Lp dams showed an increased abundance of Firmicutes compared to their Vangl2+/+ counterpart, an alteration previously observed in patients with obesity and in gestational diabetes mellitus." (PMID 38068802, 2023). "Following the results presented here, future research could consider the possibility that the microbiota of the Vangl2+/Lp females, which resembles microbiota alteration observed in gestational diabetes mellitus and obesity, could be playing a determinant role in the phenotype of this NTD model." (PMID 38068802, 2023).
glioma (1 paper, 2024). A benign or malignant brain and spinal cord tumor that arises from glial cells (astrocytes, oligodendrocytes, ependymal cells). "DLL1 overexpression mitigated the reduction in glioma cell viability and invasion caused by VANGL2 knockdown compared to control groups." (PMID 39871948, 2024). "Functional enrichment analysis of genes positively associated with VANGL2 in glioma underscored their enrichment in Notch signaling and pathway regulating pluripotency of stem cells." (PMID 39871948, 2024). "When examining the exposure-outcome relationships, it is crucial to consider the potential confounding effects of variables such as IDH mutation and grading of glioma on the observed effects of VANGL2." (PMID 39871948, 2024). "Functional enrichment analysis was performed to investigate the biological pathways associated with VANGL2 in glioma." (PMID 39871948, 2024). "High mRNA expression level of VANGL2 was significantly associated with improved overall survival (OS) in patients with glioma based on TCGA dataset (p < 0.0001)." (PMID 39871948, 2024). "VANGL2 may be implicated in the initiation and progression of glioma as a component of the hijacked signaling cascade in the early phase of tumor formation." (PMID 39871948, 2024). "We identified a significant correlation between increased VANGL2 expression and IDH mutation in glioma patients." (PMID 39871948, 2024). "The qRT-PCR assay results demonstrated a significant decrease in VANGL2 mRNA expression in the tested glioma cells following transfection with shVANGL2 #1 and shVANGL2 #2, comparing to those transfected with scrambled control shRNA (shControl)." (PMID 39871948, 2024). "To investigate the potential relationship between the Wnt/PCP pathway and cancer, we analyzed the expression of the core PCP gene VANGL2 across various cancer types, with a particular focus on gliomas." (PMID 39871948, 2024). "PCP core genes VANGL1, VANGL2, and FZD7, are upregulated in gliomas and associated with poor prognosis." (PMID 39871948, 2024). "For gliomas, mRNAsi is correlated positively with the expression level of VANGL2 (r = 0.2355, p < 0.0001)." (PMID 39871948, 2024). "This is yet further proof that Notch signaling pathway and signaling pathways regulating pluripotency of stem cells have a significant contribution to the regulatory mechanism of VANGL2 in glioma development, not only Wnt signaling pathway." (PMID 39871948, 2024). "Our analysis of the expression and prognostic features of the core PCP gene VANGL2 underscored its critical roles in glioma oncogenesis and progression." (PMID 39871948, 2024). "Taken together, these findings confirmed that knockdown of VANGL2 inhibits the metastatic ability of glioma." (PMID 39871948, 2024). "That is to say, a decrement in VANGL2 expression clearly diminished the stemness properties in glioma cells." (PMID 39871948, 2024). "Thereinto, expression profile of VANGL2 in glioma (LGG and GBM) patients represents the highest mRNA value across all cancer types in the TCGA dataset." (PMID 39871948, 2024). "In vitro experiments further confirmed that VANGL2 promotes glioma cell migration, invasion, proliferation, and tumor sphere formation." (PMID 39871948, 2024). "To further explore the function of VANGL2 gene, we performed mRNA co-expression analysis for VANGL2 in the glioma cohort using Pearson’s correlation." (PMID 39871948, 2024). "Next, we performed wound healing assay to detect whether knockdown of VANGL2 inhibits glioma cell migration." (PMID 39871948, 2024). "Given the role of VANGL2 in regulating tumor stemness, we determined whether VANGL2 affected the proliferation of glioma cells by CCK-8 assay." (PMID 39871948, 2024). "Following the identification of the Notch pathway enriched in the co-expressed gene set with VANGL2 in gliomas, we investigated whether VANGL2 promotes glioma cell proliferation through Notch pathway activation." (PMID 39871948, 2024).
glioma (continued). "In vitro experiments were conducted to assess the impact of VANGL2 on glioma cell behaviors." (PMID 39871948, 2024). "Elevated VANGL2 expression was identified as a predictor of poor prognosis in glioma." (PMID 39871948, 2024). "This study specifically investigated the impact of the core PCP gene VANGL2 on glioma." (PMID 39871948, 2024). "These analysis results suggest that VANGL2 might play certain role in tumorigenesis and cancer progression, especially in glioma." (PMID 39871948, 2024). "In conclusion, our findings propose that VANGL2 upregulation may serve as an early trigger event in glioma, and impact Notch signaling as well as polarity." (PMID 39871948, 2024). "The high expression level of VANGL2 leads to worse prognosis and VANGL2 is a non-independent prognostic factor in gliomas." (PMID 39871948, 2024). "In all grades of gliomas (LGG and GBM), VANGL2 was significantly upregulated." (PMID 39871948, 2024).
glomerulonephritis (1 paper, 2022). A renal disorder characterized by damage in the glomeruli. "Van Gogh‐like 2 (Vangl2), a core PCP protein, is required for the normal differentiation of glomeruli and podocyte-specific deletion of Vangl2 exacerbates experimental glomerulonephritis in mice." (PMID 35842494, 2022).
hearing loss (1 paper, 2024). "Finally, in a large family with dominant non-syndromic hearing loss (Family 16), exome sequencing identified a heterozygous VANGL2 c.1394A> C; p.(Glu465Ala) variant in four affected individuals and one unaffected sibling." (PMID 37815931, 2024).
hyperglycaemia (1 paper, 2015). "Maternal hyperglycaemia is known to affect the expression of components of the Wnt-PCP pathways, including Wnt5a, Vangl2, Rock1 and Daam1 in mouse embryos, suggesting that abnormal Wnt-PCP signalling might underlie diabetic embryopathies." (PMID 25540130, 2015). "Hyperglycaemia affects the activity of important signalling pathways that are crucial for mouse embryogenesis, including the hypoxia (Hif1α), PDGFRa, Wnt-β-catenin (GSK3β, β-catenin) and the Wnt-planar cell polarity (PCP) (Vangl2, Daam1, Wnt5a, etc.)pathways." (PMID 25540130, 2015).
leukemia (1 paper, 2016). A malignant (clonal) hematologic disorder, involving hematopoietic stem cells and characterized by the presence of primitive or atypical myeloid or lymphoid cells in the bone marrow and the blood. "Similarly in migrating leukemia cells, Dvl-3 (part of the Fzd complex) localizes to the leading edge while Vangl2 localizes to the trailing edge." (PMID 26990447, 2016).
lipomyelomeningocele (1 paper, 2023). Lipomyelomeningocele is a rare neural tube closure defect characterized by a subcutaneous lipoma that extends through a defect in the lumbodorsal fascia, vertebral neural arch, and dura. "We have also demonstrated that, as in human lipomyelomeningocele, closed NTDs in this Vangl2 mouse model are resistant to maternal FA supplementation." (PMID 37589570, 2023).
Lissencephaly (1 paper, 2015). A spectrum of malformations of cortical development caused by insufficient neuronal migration that subsumes the terms agyria, pachygyria and subcortical band heterotopia. "Cortical disruptions that derive from mutations in genes such as NDE1, LIS1, PP4c, WDR62, CENPE, TCOF1, AGS3, VANGL2 and HTT, are classified as micro- or macro-cephaly, and/or cortical disorganization and abnormal cortical architecture, lissencephaly and simplified gyral patterns." (PMID 25729350, 2015).
lung carcinoma (1 paper, 2020). "The potential network of circ‐IGF1R–miR‐1270–VANGL2 was preliminarily determined, and the expression patterns of miR‐1270 and VANGL2 were verified in lung cancer cell lines." (PMID 32107851, 2020).
myocardial hypertrophy (1 paper, 2024). "During myocardial hypertrophy, Vangl2 aggravates myocardial hypertrophy by regulating Wnt/c-Jun N-terminal kinase (JNK) signaling and the expansion of cardiomyocyte surface area." (PMID 39269442, 2024).
myocardial infarction (1 paper, 2020). Gross necrosis of the myocardium, as a result of interruption of the blood supply to the area, as in coronary thrombosis. "In a rat left anterior descending ligation myocardial infarction model, increased protein levels of Wnt5a, Ror2, and Vangl2—one if its immediate downstream targets—were observed in the remote vital area." (PMID 33134326, 2020).
nasal polyp (1 paper, 2023). "Immunohistochemical expressions of Dishevelled-1, Dishevelled-3, Frizzled3, Frizzled6, Prickle2 and Vangl2 were lower in the nasal polyps than in the turbinates." (PMID 38232516, 2023). "Our study also revealed decreased immunohistochemical expressions of the PCP proteins, Dishevelled-1, Dishevelled-3, Frizzled3, Frizzled6, Prickle2 and Vangl2 in the nasal polyp compared to the turbinate mucosa." (PMID 38232516, 2023). "Immunohistochemical expressions of the PCP proteins, Dishevelled-1, Dishevelled-3, Frizzled3, Frizzled6, Prickle2 and Vangl2 were lower in the nasal polyps than in the turbinate mucosae." (PMID 38232516, 2023). "In addition, we showed decreased immunohistochemical expression of Prickle2 and Vangl2 in nasal polyps, and this may also contribute to PCP disarrangement in this tissue." (PMID 38232516, 2023). "For Vangl2, weak fluorescence was observed on the surface of the turbinate mucosa, whereas the nasal polyp showed no immunoreactivity." (PMID 38232516, 2023). "The expression levels of DVL1, DVL3 and FZD3 mRNAs were significantly lower in the nasal polyps than in the turbinates, while those of FZD6, PRICKLE1, PRICKLE2, VANGL1 and VANGL2 mRNAs were not statistically different between the two tissues." (PMID 38232516, 2023).
Obesity (1 paper, 2023). Accumulation of substantial excess body fat. "However, although a higher Firmicutes/Bacteroidetes ratio has been linked to obesity, in our study, the increase in Firmicutes in Vangl2+/Lp did not translate into an altered Firmicutes/Bacteroidetes ratio." (PMID 38068802, 2023).
osteoporosis (1 paper, 2025). A condition of reduced bone mass, with decreased cortical thickness and a decrease in the number and size of the trabeculae of cancellous bone (but normal chemical composition), resulting in increased fracture incidence. "VANGL2 also inhibits osteogenesis and plays a pathogenic role in osteoporosis." (PMID 39899477, 2025).
polycystic liver disease (1 paper, 2023). "Interestingly, the present analysis identified yet another multispanning plasma membrane protein, VANGL2, that is involved in the establishment and regulation of planar cell polarity as a Sec63 client and, when absent, may also contribute to the phenotype of SEC63-linked polycystic liver disease." (PMID 37762469, 2023).
rapidly progressive glomerulonephritis (1 paper, 2021). Inflammation of the glomeruli that is characterized by a rapid loss in renal function with glomerular crescent formation observed on biopsy; it is often seen in patients with concomitant autoimmune disease, like Goodpasture's syndrome or systemic lupus erythematosus. "The NTN model mirrors human rapidly progressive glomerulonephritis (RPGN), and recently, transcripts for VANGL1, VANGL2, CELSR2, DVL2, DVL3, PK1, and PK2 were found to be significantly upregulated in two independents cohorts of RPGN biopsies compared to living kidney donor controls." (PMID 33716764, 2021).
scoliosis (1 paper, 2022). A congenital or acquired spinal deformity characterized by lateral curvature of the spine. "Remarkably, loss of Vangl2 in foxj1a-positive cell lineages causes ependymal cell cilia and Reissner fiber formation defects as well as idiopathic-like scoliosis." (PMID 36151137, 2022).
Splenomegaly (1 paper, 2022). Abnormal increased size of the spleen. "Old Vangl2-deficient mice showed increased expansion of myeloid-biased multipotent progenitor cells concomitant with splenomegaly." (PMID 35399538, 2022).
ventricular septal defect (1 paper, 2024). The presence of a defect (opening) in the septum that separates the two ventricles of the heart. "Firstly, Vangl2 mutant mice develop ventricular septal defects (VSD), but not AVSD which we report in both neonates." (PMID 37815931, 2024).
cancer (18 papers, 2014 to 2025). A tumor composed of atypical neoplastic, often pleomorphic cells that invade other tissues. "In contrast, loss of Vangl2 in fibrosarcoma cancer cells appears to increase MMP2 and MMP14 resulting in enhanced cellular migration and invasion." (PMID 35646914, 2022). "Although VANGL2 is a core component of the planar polarity complex, it also influences proliferation, cancer stemness, and other processes in tumors, beyond merely determining the direction of cell polarity." (PMID 39871948, 2024). "The results illustrate that VANGL2 was up-regulated in malignant tumors compared with the corresponding normal samples at both the transcriptome and proteome levels." (PMID 39871948, 2024). "Van Gogh-like 2 (Vangl2), a core planar cell polarity component, plays an important role in polarized cellular and tissue morphology induction, growth development, and cancer." (PMID 39269442, 2024). "Moreover, the abnormal function of Vangl2 results in various diseases, such as cancer, kidney glomerular injury, idiopathic pulmonary fibrosis, and systemic dysplasia." (PMID 39269442, 2024). "Our study underscores the close association between VANGL2 and the Notch signaling pathway, emphasizing the high involvement in Notch pathway in terms of cancer development, rather than the general Wnt pathway." (PMID 39871948, 2024). "Notably, TCGA samples exhibiting elevated VANGL2 gene expression demonstrated significantly increased cancer stemness indices compared to those with lower VANGL2 expression." (PMID 39871948, 2024). "Indeed, both Vangl1 and Vangl2 are dysregulated in diverse tumor types and, consistent with its role in mediating cell motility events in development, Vangl contributes to cancer cell migration, invasion, and metastasis [reviewed in]." (PMID 35646914, 2022). "These included cancer epigenetic targets previously implicated in tumor suppressive activity such as ANXA6 [annexin A6], VANGL2 [VANGL planar cell polarity protein 2], BIN1 [bridging integrator 1], and CREB3L1 [cAMP responsive element binding protein 3 like 1]." (PMID 34074348, 2021). "Loss of cell polarity commonly observed in carcinomas and during EMT could thus favour the formation of VANGL2–p62/SQSTM1 complex and the subsequent JNK-mediated cell proliferation." (PMID 26754771, 2016). "TMEM14A may also play a role in the regulation of planar cell polarity by trafficking planar cell polarity proteins to the membrane including VANGL2, a protein that promotes migration and invasion in human cancer cells." (PMID 24495353, 2014). "Furthermore, it will be interesting to determine whether such deregulation of mammary stem cell self-renewal, expansion and/or cell fate acquisition by VANGL2 may contribute to its cancer modulatory effects." (PMID 31068622, 2019). "Apart from recent findings that podocyte-specific deletion of Vangl2 leads to increased susceptibility to injury in adult mouse kidney following challenge, and links between PCP gene dysfunction and cancer, the role of the PCP pathway in adulthood is almost entirely unstudied." (PMID 28237967, 2017). "Our study focused on VANGL2, a core PCP gene, to elucidate its potential mechanistic involvement in cancer development." (PMID 39871948, 2024). "In migrating cancer cells, VANGL1 and VANGL2 occupy cell membrane domains opposite to Wnt/Fzd complexes, promoting protrusion formation for mesenchymal-like cell motility." (PMID 36675340, 2023). "In contrast, luminal cancers show less consistent up-regulation of SCRIB and VANGL2 mRNAs and rare up-regulation of SMURF2 or WNT11." (PMID 36675340, 2023). "Since MEC1 cells are migrating cancer cells, whose migration depends on WNT/PCP signaling with strong polarization of VANGL2-EGFP, this model has the capacity to serve as a novel and long awaited high throughput screening platform." (PMID 25627785, 2015).
cancer (continued). "VANGL2 expression was found to be heterogeneous across cell lines and higher in the basal and mesenchymal cell lines, such as SUM149 and SKBR7, than in the luminal ones, as observed in the clinical cancer samples." (PMID 26754771, 2016). "The totality of these data supports the notion that a coordinated deregulation of SCRIB, VANGL2 and NOS1AP at the gene dosage or transcription level, possibly in conjunction with other PCP protein abnormalities, may affect cancer cell behavior in a sub-type-specific manner." (PMID 36675340, 2023). "Different sub-types show different patterns of mRNA expressions in these PCP players, with most basal cancers displaying up-regulation of SCRIB and VANGL2 mRNAs in both cases where they are amplified and non-amplified for the respective genes." (PMID 36675340, 2023).